GDF5 (growth differentiation factor 5)
Diseases named in the same sentence as GDF5 in open-access papers (continued):
Sharing a sentence is not in itself a finding about the gene and the disease.
osteoarthritis (continued). "The further identification of molecules acting upstream of GDF5 will not only provide further understanding of joint formation, but will also potentially lead to insight into the pathogenesis of human joint diseases such as osteoarthritis." (PMID 23356643, 2013). "It suggests hydrolyzable tannins may affect GDF5 to modulate bone growth and osteoarthritis." (PMID 37049604, 2023). "Similarly, the GDF5 locus found in knee pain is also involved in osteoarthritis." (PMID 37144689, 2023). "Therefore, GDF‐5 appears to be a promising treatment for osteoarthritis." (PMID 32497388, 2020). "Several of these target genes such as ADAMTS5, GDF5 and LEP have been previously correlated with osteoarthritis." (PMID 19011694, 2008). "Although several core pathways are known to underpin osteoarthritis pathology, regardless of joint site affected, no common genetic osteoarthritis SNVs have been found previously, with the exception of the GDF5 locus." (PMID 34450027, 2021). "Our results show that osteoarthritis chondrocytes do not respond in a predictable manner to culture with exogenous GDF5." (PMID 24466161, 2014).
knee osteoarthritis (17 papers, 2011 to 2025). "Here, we focus on joint disorders, finding among replicated loci, that GDF5 exhibits over twenty distinct associations, and we identify causal variants for two of its strongest associations, hip dysplasia and knee osteoarthritis." (PMID 34230488, 2021). "Growth differentiation factor 5 (GDF5) rs143383 genetic polymorphisms is the association of the susceptibility of knee osteoarthritis reported in Bioscience Reports." (PMID 32928309, 2020). "Although the association of the risk of knee osteoarthritis and GDF5 rs143383 genetic polymorphisms has been described in several meta-analyses, several recent trials also reported the risk of knee osteoarthritis and GDF5 rs143383 genetic polymorphisms." (PMID 32928309, 2020). "There is significant correlation between knee osteoarthritis and GDF5 rs1433383 polymorphisms in Caucasians." (PMID 32928309, 2020). "By comprehensive analysis, there is significant relationship between knee osteoarthritis and GDF5 rs143383 polymorphisms." (PMID 32928309, 2020). "On the one hand, previous literatures have said that GDF5 rs143383 polymorphisms C allele is a protective factor for the susceptibility of knee osteoarthritis among Caucasian populations (OR = 0.74, P < 0.001) and Asian populations (OR = 0.87, P = 0.004)." (PMID 32928309, 2020). "Although previous meta-analysis literatures thought that high-expressed GDF5 rs143383(C/T) can reduce the risk of knee osteoarthritis, their limitations still remain." (PMID 32928309, 2020). "Our article has found sufficient pieces of evidences to conclude that the risk of Caucasian’s knee osteoarthritis is the association with GDF5 rs143383 polymorphisms." (PMID 32928309, 2020). "A few months ago, the Bioscience Reports journal showed that growth differentiation factor 5 (GDF5) rs143383 genetic polymorphism increases the susceptibility of knee osteoarthritis (KOA), but previous studies’ results have debates about available data." (PMID 32928309, 2020). "Furthermore, GDF5 rs143383-C (in high LD with GDF5 rs143384-G) is a protective factor with respect to susceptibility to knee osteoarthritis and stress fractures." (PMID 36292594, 2022). "Therefore, we needed to update the data of the relevant studies and aim to clarify the relationship of GDF5 rs143383 genetic polymorphisms and the risk of knee osteoarthritis." (PMID 32928309, 2020). "Previous studies investigating the association between GDF5 rs143383 polymorphism and knee osteoarthritis (OA) have suggested stronger associations in Asians than Caucasians, but limitations on the amount of available data have meant that a definitive assessment has not been possible." (PMID 25467786, 2014). "A great deal of previous meta-analysis has supported that there is a correlation between GDF5 and knee osteoarthritis (KOA), while the research results remain contradictory." (PMID 33608035, 2021). "This study aimed to determine the genetic association between Growth Differentiation Factor 5 (GDF5) gene (rs143383 T/C) single nucleotide polymorphism (SNP) and primary knee osteoarthritis (OA) in a group of Egyptian patients." (PMID 32185351, 2019). "A great deal of evidence has supported that growth differentiation factor 5 (GDF5) is associated with the occurrence of knee osteoarthritis (KOA), while their results are not consistent." (PMID 33608035, 2021). "In the research article, we firstly found that GDF5 rs143383 polymorphisms affect the risk of knee osteoarthritis in Caucasian but not in Asian, including detailed data from 16 studies in 7997 cases and 12,684 controls." (PMID 32928309, 2020). "We did not carry on the subgroup analysis by sex, because previous meta-analysis study conclude sex factor is not significant between GDF5 rs143383 polymorphism and the risk of knee osteoarthritis." (PMID 32928309, 2020).
knee osteoarthritis (continued). "But now our research shows that GDF5 rs143383 polymorphisms are only related to knee osteoarthritis among Caucasian populations by subgroup analysis, not Asian populations." (PMID 32928309, 2020). "The observed association between the presence of at least one GDF5 rs143384 A allele and greater severity of KOA and shorter stature among female patients suggests that this variant may contribute to clinical variability and disease progression in knee osteoarthritis." (PMID 41465193, 2025).
brachydactyly (11 papers, 2008 to 2025). A disease characterized by the presence of brachydactyly, including syndromic and non-syndromic forms. "GDF5 gene variants are associated with brachydactyly, chondrodysplasia, and acromesomelic dysplasia, indicating that the GDF5 gene product plays a critical role in skeletal development." (PMID 27662846, 2016). "In contrast to activating GDF5 mutations, loss of function mutations result in hypoplastic or absent skeletal elements as described for the molecular disease family of brachydactylies." (PMID 24098149, 2013). "A heterozygous loss of function mutation in GDF5 leads to a malformation of the hands, the brachydactyly type C." (PMID 24454406, 2013). "Its phenotype is very similar to that caused by mutations in Noggin, a modulator protein counteracting GDF-5 activity, and rather different to other mutations in GDF-5 found in patients with brachydactyly and Du Pan syndrome (also known as fibula aplasia complex brachydactyly)." (PMID 26385096, 2015). "Consequently, our study assembles another part of the molecular puzzle of how loss and gain of function mutations in GDF5 affect bone development in hands and feet resulting in specific types of brachydactyly and SYNS2." (PMID 24098149, 2013). "The expression of the GDF5 protein is modulated by the GDF5 gene, and rare deleterious mutations in the GDF5 gene cause several disorders of skeletal development, such as chondrodysplasias and brachydactyly, suggesting this gene has a crucial role in joint homeostasis and repair." (PMID 25467786, 2014). "Some loss‐of‐function GDF5 variants result in reduced osteogenesis or abnormal bone development, such as brachydactyly (BD), whereas some gain‐of‐function GDF5 variants cause proximal symphalangism (SYM1, OMIM #185800) and multiple‐synostoses syndrome 2 (SYNS2, OMIM #610017)." (PMID 38222807, 2024). "GDF5 was found to be a candidate pathogenic gene in the proband, who did not carry any other known brachydactyly‐related pathogenic variant." (PMID 38222807, 2024). "Variants of GDF5 are associated with chondrodysplasia, acromesomelic dysplasia, and brachydactyly, indicating that GDF5 may play a protective role in skeletal development." (PMID 27662846, 2016). "Hence, our study assembles another part of the molecular puzzle how loss and gain of function mutations in GDF5 affect bone development in hands and feet and result in specific types of brachydactyly and SYNS2." (PMID 24098149, 2013).
chondrodysplasia (11 papers, 2007 to 2025). "Loss of GDF5 function leads to severe syndromic skeletal malformations, such as Hunter‐Thompson or Grebe chondrodysplasia." (PMID 40510624, 2025). "Loss of function mutations in the human GDF5 gene have been shown to result in a number of chondrodysplasias such as Grebe and Hunter-Thompson syndromes, and a single nucleotide polymorphism in the 5′UTR of human GDF5 has also been linked to OA susceptibility." (PMID 28608822, 2017). "Loss-of-function mutations of Gdf5 have been identified as cause of reduced skeletal growth in human chondrodysplasias and brachypodism mice." (PMID 17374144, 2007). "The importance of GDF5 in cartilage biology is illustrated by the observations that mutations in GDF5 can lead to chondrodysplasias, and that a genetic SNP in the core promotor of GDF5, resulting in reduced GDF5 protein levels, is associated with OA development." (PMID 31450621, 2019).
disc degeneration (10 papers, 2012 to 2025). "On the other hand, Growth Differentiation Factor‐5 (GDF‐5) receptors are non‐angiogenic, and GDF5 gene was shown to be a susceptiblity gene for disc degeneration, suggesting that GDF‐5 can be a promising candidate to stimulate ECM." (PMID 36925718, 2023). "It has recently been suggested that genetic polymorphisms associated with knee OA [e.g., in asporin and growth differentiation factor 5] may also be related to disc degeneration." (PMID 26552449, 2015). "A correlation between GDF-5 and cytokine expression has been noted in human annulus cells in in vitro disc degeneration models where high levels of two pro-inflammatory cytokines (IL-1β and TNF-α) leads to a significant down-regulation of GDF-5." (PMID 32824547, 2020). "Indeed, in disc degeneration models using in vitro three-dimensional cultures, human annulus cells display increased expression of pro-inflammatory cytokines, such as IL-1β and TNF-α, while exposure to TNF-α and IL-1β resulted in significant downregulation of GDF-5." (PMID 32443833, 2020).
Arthritis (7 papers, 2004 to 2023). Inflammation of a joint. "The GDF5 gene product regulates bone and cartilage formation; recent selection of growth phenotypes affected GDF5 alleles, which were also associated with an increased arthritis susceptibility, especially in East Asians38,39." (PMID 32895400, 2020). "The Growth and differentiation factor 5 (Gdf5) gene is required for normal joint formation, and has been linked to risk of common arthritis in Eurasians." (PMID 27902701, 2016). "Despite the decrease in arthritis severity in vivo and diminished cell proliferation after Yap KO in vitro (p=0.023), extensive expansion of Gdf5-lineage cells in synovium during AIA was observed in both Yap WT (p<0.001) and Yap cKO mice (p<0.001)." (PMID 34844926, 2022). "The absence of GDF5 may have consequences for immune responses and macrophage function in general and for arthritis in particular." (PMID 37719786, 2023). "The three major limb phenotypes revealed by eliminating Bmpr1a with Gdf5-driven Cre include webbing between digits, lack of joint formation at specific locations in the ankle, and failure to maintain articular cartilage after birth, resulting in severe arthritis." (PMID 15492776, 2004).
breast carcinoma (7 papers, 2012 to 2024). "The overproduction of TGF-ß in breast cancer cells elicits the expression of GDF5 in endothelial cells, promoting angiogenesis." (PMID 39150915, 2024). "Based on the available reports, GDF5 can be a valuable molecular target for targeting the modulation of metastasis of lymph nodes in breast cancer." (PMID 39150915, 2024). "We noticed that GDF5 and this amplicon were both located in chromosome 20q11 area and it was reported that GDF5 protein regulates TGF-beta dependent angiogenesis in breast carcinoma MCF-7 Cells47." (PMID 31482140, 2019). "It has been reported that TGF-β produced by breast cancer cells induces the GDF5 expression in the endothelial cells, which in its turn stimulates the angiogenesis both in vivo and in vitro." (PMID 30258285, 2018). "TGFß produced by breast cancer cells induces in endothelial cells expression of GDF5, which in turn stimulates angiogenesis both in vitro and in vivo." (PMID 23226264, 2012). "These preclinical data provide a basis to develop researches aimed to validate our observations in breast tumors with the aim to use anti TGFß–peptides and anti-GDF5 antibodies as possible therapeutic tools for TGFß/GDF5–dependent breast cancer angiogenesis." (PMID 23226264, 2012). "In this paper we have shown that TGFß produced by breast cancer cells induces in endothelial cells GDF5 expression, which in turn stimulates angiogenesis both in vitro and in vivo." (PMID 23226264, 2012). "The group then moved on to culture MCF-7 breast cancer cells with OSM, IL-10, IL-11, or growth differentiation factor 5 (GDF5) rich serum." (PMID 39123444, 2024). "The proangiogenic effect of GDF5 can be regulated by anti-TGF-ß peptides and anti-GDF5 antibodies and applied as potential therapeutic tools for TGF-ß/GDF5-dependent breast cancer angiogenesis." (PMID 39150915, 2024). "Our results show that GDF5, BAHCC1, LCN2, FGF14-AS2, and IDH2 are among the top five most effective mRNAs involved in lymph node metastasis of breast cancer based on their SHAP values." (PMID 39150915, 2024). "In four main subtypes of breast cancer, elevated expression of BMPR1B and ACVR2B were seen in Luminal A subtype, while BMP4, GDF15 and ACVR1B were higher in Luminal B, TGFBR1 and BMP8A were higher in HER2 positive, BMP2, BMP6 and GDF5 were higher in TNBC." (PMID 37333824, 2023). "Furthermore, higher levels of BMP2, BMP6 and GDF5 were revealed in triple negative breast cancer (TNBC) whilst BMP4, GDF15, ACVR1B, ACVR2B and BMPR1B were relatively higher in Luminal type BC." (PMID 37333824, 2023).
Hip dysplasia (6 papers, 2018 to 2025). The presence of developmental dysplasia of the hip. "Specifically, the GDF5 rs143384 allele variant A has been associated with knee pain, hip dysplasia and hand osteoarthritis." (PMID 41465193, 2025). "These latter two findings have important ramifications to how we understand GDF5 and its association with OA and hip dysplasia/dislocation." (PMID 30388100, 2018). "Importantly, there is ample evidence revealing the importance of non-coding regulatory variants in the GDF5 locus as potentially underlying hip dysplasia’s and degenerative diseases." (PMID 30388100, 2018). "Other studies have shown the connection of this GDF5 gene locus with hip dysplasia, OA of the hand, and congenital hip dislocation." (PMID 38424630, 2024). "Several chromosomal loci that are closely associated with unilateral or bilateral hip dysplasia, such as CX3CR1, GDF5, and HOX, were identified through familial aggregation studies of multiple DDH patients." (PMID 39156961, 2024).
multiple synostoses syndrome (6 papers, 2013 to 2025). Multiple synostoses syndrome (MSS) is a rare developmental bone disorder characterized by proximal symphalangism of the fingers and/or toes often associated with fusion of carpal and tarsal, humeroradial, and cervical spine joints. "Alternately a gain-of-function mutation in GDF5 causes the persistence of cartilage and results in Proximal symphalangism or Multiple synostoses syndrome." (PMID 29371961, 2017). "Here we report on a GDF5 mutation, p.W414R, which is associated with brachydactyly type A1 (BDA1) and Multiple Synostoses Syndrome 2 (SYNS2)." (PMID 24098149, 2013). "Thus, proximal interphalangeal fusion is typically observed in multiple synostoses syndrome linked to NOG, GDF5 and FGF9 genes, while fusion of carpal and tarsal bones is observed in patients carrying a GDF6 variant." (PMID 40673520, 2025).
Obesity (6 papers, 2019 to 2025). Accumulation of substantial excess body fat. "At the same time, we obtained data on the KOA-risk role of polymorphism rs143384 GDF5 (allele G) in non-obesity individuals." (PMID 38424630, 2024). "In the present study, the effect of obesity on the association of the rs143384 GDF5 with KOA was shown: allele G of this SNP was a KOA protective factor in individuals with BMI ≥ 30 (OR 0.41) and disease risk marker in individuals with BMI < 30 (OR 1.32–1.67)." (PMID 38424630, 2024). "In summary, the effect of obesity on the association of the rs143384 GDF5 with KOA was shown: the “protective” value of this polymorphism in the BMI ≥ 30 group and the “risk” meaning in BMI < 30 cohort." (PMID 38424630, 2024). "This study showed that obesity exerted an effect on the associations of the rs143384 GDF5 with the KOA risk." (PMID 38424630, 2024). "The interaction between GDF5 gene and environment factors (smoking, drinking, and obesity) further increased the risk of KOA." (PMID 30777926, 2019). "The interaction between GDF5 gene and drinking, smoking, and obesity further increased the risk of KOA." (PMID 30777926, 2019). "This phenomenon may be attributed to the regulatory effect of the SNP on GDF5 expression within adipose tissue, highlighting a critical gene–environment interaction whereby obesity alters genetic predisposition to KOA." (PMID 41465193, 2025). "The relationship between rs143384 GDF5 and body weight, as well as various anthropometric indices (body fat distribution, waist-to-hip ratio, waist-hip index, etc.), which may be associated with overweight or obesity, was demonstrated in previously GWAS." (PMID 38424630, 2024). "At the same time, the effect of overweight and obesity on the association of GWAS-significant loci (rs8044769 FTO and rs143383 GDF5) with KOA has been examined only in a small number of studies." (PMID 38424630, 2024). "More experiments are needed to be designed and conducted to further validate the mechanism of protective role of GDF5 in obesity and COPD." (PMID 37886639, 2023). "Evaluated genotypes also included those relating to cardiovascular health (ACE), obesity and metabolism-related genotypes (FTO, UCP1, MC4R, and ADIPOQ), sweet taste perception (Tas1R2 and KCTD10), and endurance (GDF5)." (PMID 36235756, 2022). "Our recent study demonstrated that growth differentiation factor 5 (GDF5) could promote white adipose tissue thermogenesis and alleviate high-fat diet- (HFD-) induced obesity in fatty acid-binding protein 4- (Fabp4-) GDF5 transgenic mice (TG)." (PMID 33542911, 2021).
Grebe syndrome (5 papers, 2008 to 2022). "GDF-5 gene mutations (CDMP1) implicated in Hunter–Thompson type dwarfism and in Grebe Syndrome (characterized by short stature, extra digits, and short and deformed extremities)." (PMID 35629331, 2022). "Loss of function mutations in the human GDF5 gene are also found in patients with acromesomelic chondrodysplasia Hunter-Thompson syndrome, Grebe syndrome, Brachydactyly Type A2 and C." (PMID 27902701, 2016). "Multiple human congenital skeletal defects have previously been traced to coding region changes in the GDF5 gene, including: acromesomelic chondrodysplasia Hunter-Thompson syndrome, Grebe syndrome, Brachydactyly Type A2 and C and synostoses." (PMID 27902701, 2016). "Previously, GDF5 mutations have been shown to constitute the major cause of ACD Grebe and du Pan types, and BMPR1B mutations had been identified in single families with Grebe syndrome and a Grebe dysplasia-like phenotype with genital anomalies." (PMID 26105076, 2015).